TNF (tumor necrosis factor)
Diseases named in the same sentence as TNF in open-access papers (continued):
Sharing a sentence is not in itself a finding about the gene and the disease.
cancer (continued). "Encouraged by the differential effects of intrinsic and extrinsic inducers of apoptosis, we utilized cisplatin as an inducer of the intrinsic pathway and TNF-α as an inducer of the extrinsic pathway to track the expression patterns of m6A RNA methylation regulators in different cancer cell lines." (PMID 38665783, 2024). "The activation of signal transduction pathways that promote apoptosis can occur in cancer illnesses by the recruitment of death domains (DDs) containing adapters, such as the Fas-associated death domain (FADD) and TNFR-associated DD (TRADD), via TNF signaling." (PMID 39104398, 2024). "TNFα significantly increases the cell response to chemotherapy as well as the release of ATP to enhance cancer immunogenicity via the P2RX7 receptor, thus promoting DC maturation and proinflammatory cytokine production and leading to T-cell-mediated cytotoxicity." (PMID 38195677, 2024). "Several studies investigated the effect of gold derivatives on TNF-α in cancer." (PMID 38082190, 2024). "The multi-scale model of Ponce-de-Leon85 considered the Covariance Matrix Adaptation Evolutionary Strategy for the numerical optimization of their agent-based model to analyze the treatment parameters of the tumor necrosis factor cytokine and its effect on cancer regression." (PMID 38678381, 2024). "Interestingly, increased TNFα expression in cancer cells post-treatment appeared to be beneficial to PTX therapy." (PMID 39033271, 2024). "In the early stages of cancer, M1 TAMs are present, participating in the inflammatory response and expressing many pro-inflammatory cytokines such as tumor necrosis factor (TNF)-α, interleukin-2 (IL-2), IL-6, IL-12, IL-23, nitric oxide (NO) and reactive oxygen species (ROS)." (PMID 39682696, 2024). "Also, IL-6, IL-17, and TNFα were found at higher levels, which suggest that cytokines act in parallel to modulate immune responses in cancer." (PMID 38279220, 2024). "If there were a concern with remaining M-DCsTNF, for example, chronic inflammation and stimulation of cancer growth due to high level of TNFα, a bisphosphonate could be administered because it can inhibit DC activity." (PMID 39105847, 2024). "Notably, Melero and co-workers showed that anti-TNF compounds not only improve ICI efficacy but also their tolerability in preclinical cancer models, including the B16F10-Ova model." (PMID 39136013, 2024). "Considering elevated levels of TNF-α and IL-1β are found in advanced cancer and cachexia patients, these results suggest that these cytokines may be more interesting therapeutic targets." (PMID 38254849, 2024). "highlighted the modulatory effect of VEGF on cancer angiogenesis, and of TNF-α on intravasation." (PMID 38619704, 2024). "As a result, pro-inflammatory cytokines such as tumor necrosis factor-alpha (TNF-α) are stimulated, initiating pro-inflammatory mechanisms that could potentially aid in the advancement and growth of cancer." (PMID 38947385, 2024). "Physiological dysregulation of cytokines, such as tumor necrosis factor-alpha and interleukin 6, in patients with tumors may impede albumin synthesis by hepatocytes, influencing cancer progression and neoangiogenesis." (PMID 39624689, 2024). "Tumor necrosis factor, chemokines, inflammasomes, transcription factors, cytokines, infiltrating or circulating immune cells, and ROS are a few of the cancer-related inflammatory factors that contribute to the development of cancer." (PMID 38543009, 2024). "The interaction between TNF-α and NF-κB in cancer is quite complex." (PMID 39834817, 2024).
cancer (continued). "However, the effect of natural compounds on sphingolipid and TNF signaling networks during cancer immune evasion remains largely unclear." (PMID 38698424, 2024). "The reduction in IL-6 levels suggests a potential decrease in the immunosuppressive environment, which could further support the antitumor activity of TNF-α by promoting a more effective immune response against cancer cells." (PMID 39120359, 2024). "Meanwhile, a variety of cytokines were produced by M1 macrophages, including tumor necrosis factor–α (TNF-α), growth inhibitors, and anti-angiogenic factors, which could inhibit cancer progression." (PMID 38605951, 2024). "Moreover, ovarian cancer patients were found to have higher serum levels of TNF and sTNF-R compared to non-cancer subjects." (PMID 38339276, 2024). "TNF-α, particularly, has demonstrated the ability to stimulate keratinocyte proliferation, potentially contributing to cSCC development, while IL-6 and IL-11 can enhance cancer cell survival and migration, thereby bolstering cSCC growth." (PMID 40013270, 2024). "It is interesting to note that H2AFY facilitated the response of cancer cells to TNFα-NF-κB." (PMID 38245506, 2024). "High neutrophil levels in tissues secrete numerous inflammatory mediators like vascular endothelial growth factor (VEGF), tumor necrosis factor-a (TNF-a), interleukin-2 (IL-2), interleukin-10 (IL-10), and interleukin-6 (IL-6) which creates a suitable environment for cancer progression." (PMID 38166889, 2024). "Considering that T cells express S1PR and are responsive to S1P stimulation, it remains to be determined whether the A20/autophagy/sphingolipids signaling mechanism is active in TNF-α-resistant cancer cells and the TME." (PMID 38698424, 2024). "Then Th1 cells released TNF-α and Interferon gamma (IFNγ) which act as cancer suppressors." (PMID 39252305, 2024). "Some oral bacteria, such as Streptococcus and Fusobacterium, may reduce levels of short-chain fatty acids (SCFAs) and elevate tumor necrosis factor-alpha (TNF-α) and interleukin-6 (IL-6), potentially promoting cancer cell proliferation." (PMID 39456670, 2024). "In a large Phase I study involving histologically confirmed advanced cancer patients, delivering the tumor necrosis factor TNF‐α using the adenoviral vector TNFerade into patient tumors led to objective responses in 43% of patients, with 5 out of 30 patients showing complete response to treatment." (PMID 39667820, 2024). "More aggressive cancer cells grew more quickly when the cytokines TNF-α and IL-6 were present." (PMID 38506948, 2024). "Based on insights from studies in pancreatic beta cells and the CNS, it is hypothesized that ABCC8 expression in cancer cells may be significantly influenced by mechanisms involving hypoxia and inflammation, mediated by TNF-α and TLR signaling." (PMID 38396807, 2024). "Meanwhile, the destroyed bacteria and cancer cells can activate immune cells (such as macrophages, neutrophils, and dendritic cells), which release inflammatory cytokines (TNF-α and IL-1β) and reduce anti-inflammatory cytokines (IL-10), thereby further enhancing the efficacy of cancer immunotherapy." (PMID 38472176, 2024). "The result showed that Hepatitis B signaling pathway, Apoptosis signaling pathway, Measles signaling pathway, TNF signaling pathway signaling pathway, Pathways in cancer, and Pathways of neurodegeneration-multiple diseases were the significant pathways in the anti-PD effect of UA." (PMID 39108896, 2024). "However, a high level of TNF-α potentially promotes cellular transformation, cancer growth, and invasion." (PMID 40259956, 2024).
cancer (continued). "So inhibition of NF-κB or anti-TNF-α may offer an attractive combined strategy for immunomodulatory cancer therapy." (PMID 39493763, 2024). "TNF is a potent pro-inflammatory cytokine involved in various cancers." (PMID 39689117, 2024). "Furthermore, in the cocultures of CAFs and DU 145 cancer cells, the blockage of TNF-α by the neutralizing antibodies against TNF-α, TNFR1, and TNFR2 effectively eliminated the increase in Fgf9 secretion by CAFs caused by KLF5KR knockin." (PMID 38781024, 2024). "Macrophages directly induced apoptosis of human cancer cells through zebrafish TNF signaling." (PMID 39114912, 2024). "TNF-α is a mediator exerting therapeutic effects against cancer." (PMID 38789573, 2024). "CCRA patients with concomitant AID are the most suitable candidates for this approach, but diagnosing AID in cancer patients using traditional iron biomarkers is challenging, due, for example, to ferritin upregulation by tumor necrosis factor-alpha (TNF-a) and pro-inflammatory cytokines." (PMID 38628673, 2024). "Also, the innate immune cells present in the TME secrete cytokines, including IL-6, TNF-α, and IL-1, which, through recruiting more of the inflammatory cells, further potentiate this effect, contribute to cancer cell proliferation and survival." (PMID 39201656, 2024). "In cancer models, TNF-α, IL-6, and IL-8 strongly induce cell migration and in vivo metastasis." (PMID 38612423, 2024). "Tumor necrosis factor-related apoptosis-inducing ligand (TRAIL), a key member of the tumor necrosis factor (TNF) superfamily, selectively induces apoptosis in cancer cells by binding to death receptors 4 and 5 (DR4/5), triggering intracellular signaling and leading to programmed cell death." (PMID 39451526, 2024). "Also, the concentration of TNF-α in tears can be monitored by a rapid and simple assay, which is important for early screening and assessment of cancer." (PMID 39867928, 2024). "Interestingly, our study noted that both IL6 and TNFα levels were significantly higher in the control population compared to the cancer population, although the significance was lost when the adjusted p-value was used for TNFα." (PMID 38339282, 2024). "Similarly, cocultures using CD8 + T cells from mice that received VSV-FAST viruses alone or in combination with immunotherapy exhibited increases in the release of the proinflammatory anti-cancer cytokines IFNγ and TNF into the culture supernatant." (PMID 38750591, 2024). "TNFα is an important mediator of immune cytotoxicity in cancer." (PMID 39392349, 2024). "Similarly, TNFα produced by cancer and inflammatory cells within the TME can also recruit Tregs and impair immune surveillance by suppressing T-cell responses and the cytotoxic activity of activated macrophages." (PMID 39456771, 2024). "When T-cells are incubated with cancer cells, we observe T-cell-intrinsic cytokine secretion, which to a certain extent, may predict in vivo immune toxicity by level of hyperproduction of TNFα, IFNγ, MCP-1, and others." (PMID 39594640, 2024). "TNF-α is a cytokine of pleiotropic biological activities and of major importance in cancer progression through the modulation of processes such as inflammation, immune cell functionality, angiogenesis, cell proliferation without inducing their differentiation, and apoptosis." (PMID 39201656, 2024). "It is worth noting that the cytokines IL-33 and TNF-α, which were observed in the supernatants of the cells treated with AgNPs, have previously been documented as being produced by cancer cells undergoing apoptosis and playing a role in the signalling of dendritic and natural killer cells." (PMID 38575697, 2024). "Indeed, TBMS1 reduced the number of cancer cells adhering to VECs that were pre-activated with tumor necrosis factor alpha (TNF-α), which regulated the expression of adhesive molecules through NF-κB signaling." (PMID 38230220, 2024).
cancer (continued). "A significant finding emerged when researchers revealed that the inhibition of tumor necrosis factor alpha (TNF-α) could effectively maintain LV function, all while ensuring the anti-cancer effects of anti-PD-1 therapy remain uncompromised." (PMID 38482205, 2024). "Notably, our treatment impacted key anti-apoptotic genes such BCL2 family protein which has dual regulatory functions in apoptosis, and TNF, a potent pro-inflammatory cytokine involved in various cancer types." (PMID 39689117, 2024). "The rising levels of TNF-α in response to Sorafenib treatment further support the hypothesis, suggesting an overlap between Sorafenib’s effects and necrotic events in cancer cells." (PMID 39795937, 2024). "In addition to the prototypical inflammatory cytokines such as TNFα, IL-1s and IL-6 whose role in cancer has been largely described, novel players are entering the scene." (PMID 39359726, 2024). "In addition, NS5A proteins have the ability to obstruct the action of proapoptotic proteins, like caspase-3, Bcl-2, and necrosis factor alpha (TNF-α), which are essential for anti-cancer protection." (PMID 38898936, 2024). "Importantly, the interplay of TNF-α with two seemingly distinct entities, cancer, and DM, warrants in-depth investigation." (PMID 38406163, 2024). "Zinc nanoparticles may stimulate the synthesis of cytokines, such as the tumor necrosis factor-α (TNF-α), which plays an important role in cancer development prevention." (PMID 38732186, 2024). "Elevated levels of TNF in OC ascites have also been associated with elevated expression of the adhesion molecule VCAM‐1 on mesothelial cells, thereby enabling cancer‐mesothelial cell interactions leading to cancer cell attachment and invasion." (PMID 38566518, 2024). "Moreover, NF-κB regulates the release of cytokines and inflammatory factors, including interleukins (ILs) and tumor necrosis factor-α (TNF-α) during cancer progression." (PMID 39014491, 2024). "This may possibly be mediated through a mechanism that might involve, for example, the IL-18 receptor, which usually facilitates the secretion of molecules with anti-cancer activities, such as TNF-α and nitric oxide." (PMID 39539962, 2024). "Cancer spreading (metastasis) may also be triggered by TNF-α via the epithelial-to-mesenchymal transition (EMT) process." (PMID 38698424, 2024). "Therefore, co-treatment of bazedoxifene with LCL161 and birinapant greatly sensitises the cancer cell to TNF-mediated apoptosis." (PMID 38600086, 2024). "This particular distribution may have contributed to the lower levels of IL6 and TNFα in the plasma of the cancer group." (PMID 38339282, 2024). "However, the overall impact of these cytokines on cancer is complex, given that some factors like IL-6 and TNF-α can have both pro-tumorigenic and anti-tumorigenic effects." (PMID 39427065, 2024). "Additionally, a proinflammatory cytokine secreted by TAMs in the TME, i.e., TNF-α, is known to support cancer cell invasion." (PMID 39003350, 2024). "Moreover, TNF and nuclear factor-kappa B (NF-kB) signaling pathway performs vital functions in various cancers and immune responses." (PMID 39301019, 2024). "Tumor necrosis factor (TNF) plays a role in cancer genesis and progression." (PMID 39519281, 2024). "Neutrophils are attracted to the TME in response to TNF-α and IL-12 secreted by cancer cells." (PMID 39195299, 2024). "These interactions, which influence targets associated with the cancer immune response, suggest that BJIKT enhances T cell function and TNF signaling and suppresses TGF-β signaling, leading to cell cycle arrest, apoptosis, and amplification of pembrolizumab’s anticancer effects." (PMID 39459546, 2024).
cancer (continued). "TNF-α has an important role in inflammation and its involvement in inflammation-driven cancer." (PMID 38276239, 2024). "A previous study has shown that lymphocyte-derived IFNγ and TNF within tumors can induce senescence in numerous murine and human cancers, which may be one of the mechanisms for the dormancy." (PMID 38216787, 2024). "Furthermore, DMB consumption was negatively associated with Streptococcus thermophilus, Streptococcus pneumoniae, Streptococcus dysgalactiae, and Streptococcus agalactiae and with TNF-α plasma concentrations in patients with cancer and taste disorders." (PMID 39410033, 2024). "Similarly, TNFα can promote cell death of target cancer cells, while a range of immune cells express TNFR2 and intracellular signalling molecules which can mediate NF‐κB activation and immune cell function." (PMID 38707997, 2024). "Further research is required to define which players within the TNF-α network may be responsible for the cancer-tolerating transformation of TAMs (often defined as de-differentiation) and whether sphingolipids can be targeted in TAMs." (PMID 38698424, 2024). "Excess body fatness is linked to elevated levels of hormones and substances from fat cells that promote inflammation, such as leptin, TNF-α, and IL-6, which could potentially stimulate the growth of cancer cells." (PMID 39317703, 2024). "Next, we showed that cancer cell clearance highly depends on TNF signaling." (PMID 39114912, 2024). "There is a possibility that cancer-induced transformation of SphK/S1PRs signaling is responsible for the development of TNF/TRAIL resistance in cancers, although the hypothesis remains untested." (PMID 38698424, 2024). "PL EO can exert its anti-inflammatory effects by several mechanisms, Firstly, anti-inflammatory activities can reduce cancer by the attenuating the pro-inflammatory cytokines production, such as TNF-α and IL-6, which have been shown to promote cancer growth and progression." (PMID 38635559, 2024). "Some cancers, especially hematologic cancers, may release cytokines like IL-1, IL-6, and TNF-α, that negatively impact megakaryocytes and suppress platelet production, explaining some cases of cancer-associated thrombocytopenia." (PMID 39114075, 2024). "Despite the knowledge that TNF-α supports apoptosis, the knock-out of this cytokine can upregulate different pro-apoptotic signaling in certain BC subtypes that regulate specific molecular mechanisms that direct the cancer cells toward death." (PMID 38464730, 2024). "Gene ontology (GO) term analysis highlighted the enrichment of signaling pathways related to the early and late responses to OVs in cancer cells including interferon gamma and alpha response, TNF signaling via NF-κB and apoptosis that were all being affected by the 4-OI treatment." (PMID 38750019, 2024). "Many other cells, including T cells and monocytes, could also be engineered to target delivery of TNFα to cancer cells in combination with an IAP antagonist because an IAP antagonist enables TNFα to rapidly induce apoptosis in a broad range of cancers." (PMID 39105847, 2024). "It was later discovered that administering high doses of TNF-α directly to cancer cells could induce cell death, although this effect typically occurs in combination with other growth-inhibiting antimetabolites." (PMID 39830670, 2024). "As we previously showed that LUBAC acts as a gatekeeper for cell death induction by TNF, FasL and TRAIL, independently of NF-κB regulation, we next examined whether LUBAC deficiency could sensitize cancer cells to death induced by LTβR activation." (PMID 39215104, 2024). "The manipulation of TNF-α and its downstream pathways may offer newer therapeutic opportunities for cancer prevention." (PMID 39246660, 2024).